MYCN (MYCN proto-oncogene, bHLH transcription factor)
Diseases named in the same sentence as MYCN in open-access papers (continued):
Sharing a sentence is not in itself a finding about the gene and the disease.
neuroblastoma (continued). "Amplification of MYCN is observed in high-risk neuroblastomas (NBs) and is associated with a poor prognosis." (PMID 38390263, 2024). "We compared the potential association of DEGs and DSGs with neuroblastoma prognosis, specifically with the MYCN-157 gene signature that was found to have greater prognostic power than MYCN amplification status." (PMID 39313128, 2024). "According to reported studies, MYCN mutations have been strongly linked to neuroblastoma by upregulating the expression of the iron import transferrin receptor and targeting the Xc- system/glutathione (GSH) pathway." (PMID 38536014, 2024). "MYCN mutations is a known aggravating factor in paediatric cancers and defines severe subtypes of medulloblastoma and neuroblastoma." (PMID 37606819, 2024). "Using an unbiased large-scale mutagenesis screen in neuroblastoma-prone transgenic mice, we identify a single germline point mutation in the transcriptional corepressor Runx1t1, which abolishes MYCN-driven tumorigenesis." (PMID 38992040, 2024). "Very few responses were reported in patients with MYCN amplification, which is commonly seen in young children with high-risk neuroblastoma." (PMID 39177282, 2024). "Childhood neuroblastoma with MYCN amplification is classified as high risk and often relapses after intensive treatments." (PMID 39255035, 2024). "The International Neuroblastoma Risk Group Staging System regards tumor differentiation grade, histological category, stage, age, MYCN amplification status, DNA ploidy, and chromosome 11q status as the most important prognostic features." (PMID 38495105, 2024). "Research on MYCN is primarily focused on neuroblastoma, and its proliferation is linked to undifferentiated morphology and a worse prognosis." (PMID 38315329, 2024). "Mutations in the chromatin remodeler ATRX and its partner DAXX are strongly associated with ALT while MYCN amplification is observed in telomerase-dependent/ALT-negative neuroblastomas." (PMID 38837897, 2024). "Neuroblastoma (NB) is a solid pediatric tumor of neural crest origin characterized by the amplification of the MYC family member MYCN oncogene in ∼25% of cases, which correlates with high-risk disease and poor prognosis." (PMID 39715212, 2024). "Cases exhibiting risk factors, such as amplified MYCN, show comparable results to high-risk unilateral neuroblastoma carrying the same prognostic features." (PMID 38607453, 2024). "Although the oncogene MYCN plays a crucial role in neuroblastoma and is associated with poor outcomes, amplification is observed in less than 25% of tumors." (PMID 39595172, 2024). "Amplification of the transcription factor MYCN occurs in about 20 to 25% of neuroblastoma and is associated with high-risk disease." (PMID 38820154, 2024). "MYCN amplification accounts for nearly 25% of patients and is one of the most significant biomarkers for high-risk neuroblastoma, correlating with both disease advancement and poor survival." (PMID 38214542, 2024). "The disease is noteworthy for its broad spectrum of clinical behavior and can be classified into three risk groups (low, intermediate, and high risk) based on age, MYCN status, and histology, as defined by the International Neuroblastoma Staging System (INSS)." (PMID 39338204, 2024). "The results of the Koster study showed that 10 protein transcription modules centered on the positive feedback loop of TEAD4-MYCN became regulatory drivers of high-risk subtypes associated with the expansion of invasive neuroblastoma subtype (MYCN)." (PMID 39575432, 2024). "Chromosomal aberrations in this model, e.g., 17q gain and MYCN amplification, resembled those in human high-risk neuroblastoma." (PMID 38666930, 2024). "High-risk neuroblastomas are in a group of tumors with oncogene-induced RS because of MYCN amplification and frequent ALK mutations." (PMID 38279263, 2024).
neuroblastoma (continued). "Among high-risk neuroblastoma with MYCN amplification, weak cell membrane staining of CD47 was detected and high CD47 expression was detected on neurites of the tumor cells." (PMID 38920727, 2024). "First, amplification of the oncogene MYCN, which is the most frequent genetic alteration seen in high-risk neuroblastoma." (PMID 38837897, 2024). "Among them, MYCN has attracted attention for its causal role in the development of neuroblastoma and other childhood tumours." (PMID 39177021, 2024). "The International Neuroblastoma Risk Group Staging System (INRGSS) defines the high-risk group to include patients with MYCN-amplified tumours and patients > 18 months old with metastatic tumours." (PMID 38553589, 2024). "Neuroblastoma (NB) childhood cancers, associated with amplification of the MYCN oncogene, present an undifferentiated phenotype and are challenging to treat." (PMID 39528654, 2024). "MYCN-driven replicative stress has already been shown to increase susceptibility to PARP inhibition in neuroblastoma, further rationalizing the combination of PRMT5 and PARP inhibition for MNA neuroblastoma." (PMID 39313128, 2024). "One of the first oncogenes to be associated with a poor outcome in neuroblastoma was MYCN, appearing amplified in more than 25% of primary neuroblastoma tumors." (PMID 38791942, 2024). "Patients with high-risk neuroblastoma and MYCN amplification have approximately a 40–50% overall survival, despite intensive multi-modal therapies." (PMID 38869684, 2024). "Expression of EZH2, a transcriptional target of MYCN, is associated with neuroblastoma outcome, and inhibition of this histone methyltransferase by genetic or pharmacologic means, leads to neuroblastoma growth inhibition." (PMID 38992040, 2024). "We find that loss of SAGA complex KAT activity in MYCN-amplified neuroblastoma, through modulation of TADA2B, leads to a rapid and global loss of acetylation on H3K9, including in the promoters of actively transcribed genes." (PMID 38820154, 2024). "MYCN proto‐oncogene, bHLH transcription factor (MYCN) amplification is associated with aggressive retinoblastoma (RB) and neuroblastoma (NB) cancer recurrence that is resistant to chemotherapies." (PMID 37975412, 2024). "The earliest defined driver of poor prognosis neuroblastoma is gene amplification of the MYCN proto-oncogene which encodes a transcription factor of the myc-family." (PMID 39313128, 2024). "Neuroblastoma with bilateral blindness is rare in the clinic, mostly in children of young age, and is often associated with MYCN amplification and multiple metastases." (PMID 38403682, 2024). "In neuroblastoma, where the amplification of the MYCN oncogene is commonly associated with poor prognosis, N-MYC upregulates DDX21 transcription." (PMID 39769343, 2024). "Isogenic human stem cell models thus represent a clean system to elucidate the mechanism by which ALK and MYCN cooperate in high-risk neuroblastoma." (PMID 38451815, 2024). "MYCN amplification has been associated with undifferentiated, aggressive characteristics of neuroblastoma in many studies." (PMID 38685086, 2024). "The poor prognostic risk factors of locoregional neuroblastoma (LR-NB) include age, MYCN or MDM2-CDK4 amplification, 11q, histology, diploidy with ALK or TERT mutations, and ATRX aberrations." (PMID 38730688, 2024). "In summary, neuroblastoma with binocular blindness is rare in the clinic, mostly in children of young age, and is often associated with MYCN amplification and multiple metastases." (PMID 38403682, 2024). "The MYCN oncogene is amplified in approximately 20% of neuroblastomas and is the most well-defined oncogenic driver and indicator of poor prognosis in neuroblastoma, an essential feature for risk group stratification in neuroblastoma." (PMID 38809883, 2024).
neuroblastoma (continued). "Mice with a disrupted CLU gene are more susceptible to developing neuroblastomas when MYCN is transgenically expressed, suggesting that the MYCN-CLU axis is crucial and that CLU acts as a repressor in tumorigenesis." (PMID 39253532, 2024). "Amplification of MYCN is observed in ~25% of neuroblastomas and is associated with unfavorable outcome." (PMID 38413795, 2024). "Enforced reduction of MYCN expression in neuroblastoma cells is also associated with cell differentiation." (PMID 39079981, 2024). "The splicing specificity created by SNRPD3 and MYCN alongside the observed 100% survival in xenografted mice with depleted SNRPD3 expression suggests that neuroblastoma cancer cells are susceptible to therapeutic inhibition of SNRPD3." (PMID 38049564, 2024). "Recent research has shown that increased expression levels of the lncRNA myocardial infarction associated transcript (MIAT) are associated with MYCN amplification in neuroblastoma tissue and cell lines." (PMID 38891878, 2024). "Deletion or loss of heterozygosity (LOH) at chromosome 1p36 is observed in approximately 23% of neuroblastomas and is strongly associated with MYCN amplification and decreased EFS." (PMID 38809883, 2024). "Amplified MYCN oncogene is a well-known genetic alteration associated with poor prognosis in neuroblastoma." (PMID 38908072, 2024). "High-risk neuroblastoma (NB) with amplification of the MYCN oncogene is an aggressive extra-cranial solid tumor in infants and young children, which accounts for 20% of the total disease cases." (PMID 39255035, 2024). "In contrast to FS1 phenotypes, a de novo MYCN missense variant, p.(Thr58Met), is identified in a 15-year-old patient with megalencephaly, postaxial polydactyly, and neuroblastoma." (PMID 38884091, 2024). "Direct targeting of Aurora-A illuminates an exciting new venture to combat the undruggablity of MYCN, particularly in high-risk neuroblastoma." (PMID 37414143, 2023). "MYCN amplification has been found in 25% of neuroblastoma cases and tags high-risk neuroblastoma, metastatic progression, and poor prognosis." (PMID 37765276, 2023). "Most patients <18 years of age with MYCN-amplified/ALK-mutated neuroblastoma (6/7, 86%) had PD before or by the end of course 2, whereas one patient had MR." (PMID 37012551, 2023). "MYCN regulates early sympathoadrenal development in the developing fetus and alterations to its expression are associated with neuroblastoma." (PMID 37958555, 2023). "The insulin-like growth factor 2 mRNA-binding protein 1 (IGF2BP1) is an oncofetal RNA-binding protein with reported gene gain and suggested MYCN-associated roles in neuroblastoma." (PMID 37246217, 2023). "The focus of this review is to explore the novel mechanisms underlying tumor metastasis in MYCN-driven neuroblastoma." (PMID 37274289, 2023). "Approximately half of the diagnosed neuroblastoma cases are classified as high-risk, with 20–30% featuring MYCN amplification." (PMID 38087370, 2023). "Another group of high-risk neuroblastoma has hemizygous loss of chromosome 11q and is inversely correlated with MYCN; this relationship is found in 70% of all metastatic tumors." (PMID 37759629, 2023). "High-risk neuroblastomas also usually express MYCN gain of function mutation, which is a proto-oncogene leading to uncontrolled cell proliferation." (PMID 37206500, 2023). "Apart from MYCN amplification, chromosomal deletions have also been implicated in the pathogenesis of neuroblastoma." (PMID 37206500, 2023). "Dong and colleagues have reported the first genetic evidence linking GAS7 deficiency and metastasis in MYCN-driven neuroblastoma." (PMID 37274289, 2023). "Clinically, neuroblastoma is divided into low- and high-risk, depending on the age at diagnosis, stage, tumor histology, MYCN status, and tumor cell ploidy." (PMID 37765276, 2023). "The TH-MYCN transgenic mouse model mimics the development of human high-risk neuroblastoma and provides strong evidence for the oncogenic function of MYCN." (PMID 37958555, 2023).
neuroblastoma (continued). "Approximately 25% of neuroblastomas exhibit amplification of the oncogene MYCN which is the strongest correlate for high-risk disease and poor prognosis." (PMID 37415185, 2023). "The current risk classification system, stage and MYCN status have been widely recognized as neuroblastoma prognostic factors." (PMID 37834394, 2023). "Recently, we have found a DNA methylation profile in high-risk neuroblastoma that discriminates between the main groups within high-risk: MYCN-amplified and 11q-deleted." (PMID 37251933, 2023). "Neuroblastoma harbors a variety of genetic changes, including a high frequency of MYCN amplification, loss of heterozygosity at 1p36 and 11q, and gain of genetic material from 17q." (PMID 37765276, 2023). "It was especially effective against high XIAP-expressing cell lines which also happened to be MYCN-amplified, a classical hallmark of aggressive and resistant neuroblastoma." (PMID 37874199, 2023). "Another lncRNA upregulated by MYCN is the “lncRNA highly expressed in neuroblastoma 1” (lncNB1), and it is linked to poor prognosis." (PMID 38069407, 2023). "Genetic copy number variations, particularly MYCN amplification and 1p deletion, are implicated in the progress of neuroblastoma." (PMID 37904225, 2023). "Some high-risk neuroblastoma tumors display somatic amplifications/mutations in oncogene drivers, such as MYCN, ALK, PTPN11, ATRX and NRAS." (PMID 37251933, 2023). "Low-risk neuroblastomas share similarities to differentiated late sympathoblasts (also named neuroblasts in the context of neuroblastomas), whereas high-risk MYCN-amplified neuroblastomas resemble more undifferentiated sympathoblasts." (PMID 37361539, 2023). "These mice developed neuroblastoma with recurrent chromosomal copy number abnormalities, highlighting that genetic mutations coinciding with MYCN overexpression are involved in the transformation of neuroblasts and disease genesis." (PMID 37414143, 2023). "MYCN, a member of the Myc family that encodes transcription factors, plays a critical role in neuroblastoma tumorigenesis, including promoting cell growth, differentiation, and development of aggressive phenotypes." (PMID 37991019, 2023). "In neuroblastoma, where amplification of MYCN is an indicator for high-risk disease, MYCN copy number status can be determined by ddPCR using cfDNA in blood plasma." (PMID 37664065, 2023). "A previous study showed that the SE regulator CDK7 inhibitor THZ1 caused significant tumor regression in MYCN-amplified neuroblastoma cells and affected RUNX1 transcription in Jurkat T-ALL cells." (PMID 37501079, 2023). "Nemorosone was highly potent in killing HT1080 fibrosarcoma cell lines and high-risk MYCN-amplified IMR-32 neuroblastoma cells." (PMID 36899871, 2023). "We selected the MYCN-driven mouse neuroblastoma cell line 9464D because it has low mutational burden and was not responsive to ICB treatment." (PMID 36757800, 2023). "MYCN, an oncogene that is found to be amplified in around 25% of neuroblastomas, correlates with a poor prognosis and indicates a high-risk designation in all scenarios." (PMID 37628301, 2023). "MYCN, encoding the transcription factor, N-Myc is frequently amplified in neuroblastomas, another type of NE tumor." (PMID 36711033, 2023). "We reveal a novel, druggable feedforward loop of IGF2BP1 (17q) and MYCN (2p) in high-risk neuroblastoma." (PMID 37246217, 2023). "Neuroblastoma subtypes are also related to loss of heterozygosity for 1p, which is associated with tumors showing MYCN amplification, and the loss of 11q material, which is associated with a gain of 7q and 3p and a loss of 4p." (PMID 37759629, 2023). "We demonstrated that IGF2BP1 modulates MYCN expression in neuroblastoma cell models, but the underlying mechanisms and potential synergy of both in promoting HRN remained elusive." (PMID 37246217, 2023). "LIN28B, a neuroblastoma susceptibility gene that is involved in disease initiation, promotes MYCN expression." (PMID 37991019, 2023).
neuroblastoma (continued). "Tissue diagnosis is required to confirm the diagnosis of neuroblastoma and to perform molecular studies to establish risk group status including: histology, grade of tumor differentiation, MYCN amplification status, and chromosomal aberrations of the tumor." (PMID 36832517, 2023). "One mechanistic function of RUNX3 in neuroblastoma is its facilitation of the proteasomal degradation of MYCN, whereas several other underlying mechanisms have been suggested for its tumor suppressor activity in other type of cancers." (PMID 36831211, 2023). "High-risk neuroblastoma classification depends on a number of factors, including MYCN amplification status, disease stage, patient age at the time of diagnosis, chromosomal aberrations, tumor histology, and tumor cell ploidy." (PMID 36068918, 2023). "Stage, age, histologic category, grade of tumor differentiation, the status of the MYCN oncogene, chromosome 11q status, and DNA ploidy were used as the classification basis for the International Neuroblastoma Risk Group Staging System19." (PMID 37479876, 2023). "ALK amplification is also observed in approximately 15% of MYCN-amplified primary neuroblastomas, associating with worsened clinical outcomes." (PMID 37414143, 2023). "In the current study, we showed that aggressive, high-risk MYCN-amplified neuroblastoma cells tend to express a higher level of XIAP." (PMID 37874199, 2023). "Recently, we, and others, have uncovered that high‐risk MYCN‐amplified neuroblastomas are characterized by a striking GPX4 dependency." (PMID 37435859, 2023). "MYCN amplification is present in approximately 20% of high-risk neuroblastoma cases, which is associated with suppressing the functional immunity pathways and immune cell infiltration into tumors." (PMID 36068918, 2023). "MYCN is implicated in many pediatric embryonal tumors such as neuroblastoma (NB), rhabdomyosarcoma, medulloblastoma and more recently in therapy-resistant adult cancers including subtypes of breast cancer and prostate cancers." (PMID 37781575, 2023). "In agreement with their common etiology associated with defective HRR, ID6 followed the same prevalence distribution as SBS3, corroborating the predominance of defective HRR in high-risk non-MYCN-amplified neuroblastomas (p < 1.8 × 10−2)." (PMID 37868040, 2023). "The most common genetic alterations in neuroblastoma are MYCN amplification, anaplastic lymphoma kinase (ALK) mutations, segmental chromosomal alterations, and DNA copy number alterations." (PMID 37213274, 2023). "Increased ALDH18A1 in MYCN-amplified neuroblastoma is associated with amino acid and nucleotide metabolism, thus supporting the cell proliferation and self-renewal potency of cancer cells." (PMID 37835497, 2023). "The COG-564x PDX model was generated from a post-mortem blood-draw from a patient with high-risk MYCN-amplified neuroblastoma who had suffered multiple relapses." (PMID 37938771, 2023). "More than 40% of high-risk neuroblastoma (NB) cases are characterized by aberrations in the transcription factors MYCN and c-MYC." (PMID 37760568, 2023). "A4 demonstrates promising efficacy in prolonging the survival of high-risk, MYCN-amplified neuroblastoma PDXs despite having weaker binding affinity for XIAP than Smac mimetic BV6." (PMID 37874199, 2023). "Neuroblastoma constitutes approximately 8% of all cancers in children and out of which, around 25% are high-risk NBs with MYCN amplification." (PMID 37046804, 2023). "Taken together, these findings indicate the important role of MYCN in the underlying molecular mechanisms of PI3K/MYCN/VEGF regulation of critical angiogenic pathways in neuroblastoma." (PMID 37274289, 2023). "Akt activation, as denoted by an activatory phosphorylation status, has been linked to advanced disease in neuroblastoma, correlating with MYCN-amplification and poor prognosis." (PMID 37414143, 2023).